SIRT1 (sirtuin 1)
Diseases named in the same sentence as SIRT1 in open-access papers (continued):
Sharing a sentence is not in itself a finding about the gene and the disease.
Stroke (continued). "We found that SIRT1 protein expression and phosphorylation of JNK/ERK/MAPK and AKT were upregulated in the stroke patients compared with the control." (PMID 33737560, 2021). "TGR5 siRNA and BRCA1 siRNA significantly inhibited expressions of BRCA1 and Sirt1, aggravated BBB permeability and exacerbated stroke outcomes after MCAO." (PMID 32381096, 2020). "The results highlight TGR5/BRCA1/Sirt1 signaling as a critical contributor to alleviate BBB damage and as a novel target for brain edema in diseases characterized by BBB damage, such as stroke, inflammatory diseases, and neurodegenerative diseases." (PMID 32381096, 2020). "However, the role of SirT1 in the regulation of post‐stroke muscle atrophy remains unknown." (PMID 32676579, 2020). "It has been reported that activation of sirtuins, particularly SIRT-1, may protect neurons against apoptosis, inflammation and oxidative stress, suggesting that these enzymes might be new targets for treating neurological disorders such as stroke, AD and Parkinson's disease (PD)." (PMID 30301188, 2018). "miRNA-200b-5p negatively regulates SIRT1 translation and is downregulated by myc proto-oncogene protein (MYC, c-myc) in stroke model systems, showing a negative correlation with SIRT1 expression." (PMID 40724883, 2025). "An increased expression of SIRT1 and proteins essential for autophagy, including Beclin 1, autophagy-related proteins ATG3, ATG5, ATG7, ATG12-5, and LC3-II/I, was observed postmortem in the brains of stroke patients." (PMID 40724883, 2025). "It is not surprising that SIRT1 is subject to epigenetic regulation, but identifying the elements of its regulation in stroke enables targeting them for therapy and prevention of this disease." (PMID 40724883, 2025). "It alleviates ischemia/reperfusion-induced neuronal injury in a high-glucose environment by activating the Akt/SIRT1/Nrf2/HO-1 pathway in HT22 hippocampal neurons, indicating a potential role in mitigating oxidative stress and neuronal apoptosis following stroke." (PMID 40277696, 2025). "However, further experimental studies are needed for a better understanding of SIRT1/MAPK/AKT signaling cascade and its modulation on stroke outcome, which indicates a profound application value." (PMID 33737560, 2021). "Another SIRT1 activator, citicoline (CDP-choline) was effective for patients with moderate stroke." (PMID 34680562, 2021). "The examination of the expression levels and subcellular localization of SIRT1 showed no substantial change in SIRT1 expression on SP600125 treatment compared with the brain tissues of stroke rats." (PMID 33737560, 2021). "Precisely, muscle‐specific SirT1 gain‐of‐function mice are resistant to the stroke‐induced muscle atrophy as evidenced by no changes in the muscle mass and the expression levels of Atrogin‐1 and MuRF‐1 genes." (PMID 32676579, 2020). "Finally, we confirmed that SirT1 inhibits ZNF216 gene expression by blocking PARP‐1 activity and that inhibition likely plays a role in reversing post‐stroke muscle atrophy." (PMID 32676579, 2020). "To date, there was still no information about the effects of PARP inhibition on SIRT1 in experimental models of stroke and TBI." (PMID 24586272, 2014). "Surprisingly, despite its pleiotropic effects on the outcome of stroke, the effect of SIRT1 on recovery from an ischemic insult is not clear." (PMID 21910904, 2011). "In addition, other studies identified that Sirtuin 1 and reactive oxygen species play a significant role in TRAF6-mediated neuronal damage after stroke, and TRAF6 inhibition displayed neuroprotective effects in ischemic stroke via mitigating oxidative stress and neuroinflammation." (PMID 38267979, 2024). "On the one hand, Sirt1 induced the deacetylation of QIK 6; on the other hand, Sirt1 activated PPARγ/PGC-1α Signal pathway, both of which could promote synthesis of triglyceride and inhibit neuronal apoptosis, thus slowing the progression of stroke." (PMID 37622049, 2023).
Stroke (continued). "However, there is no direct evidence to prove that the Sirt1/MAPT pathway plays a role in stroke directly through antioxidant responses." (PMID 36105479, 2022). "The different changes in SIRT1 expression (compensatory rise vs no change) may be due to the different disease models (stroke vs POCD) and the different techniques used (genetic knockout vs virus injection)." (PMID 33541361, 2021). "Therefore, Sirt1-mediated inhibition of HMGB1 release, or neutralization of HMGB1 from endothelial cells might be a target for the prevention of post-stroke neurodegeneration." (PMID 33318474, 2020). "In a study with SIRT1 transgenic mice, where human SIRT1 was overexpressed under the control of rat neuron-specific enolase promoter, no neuroprotection was observed against stroke as SIRT1 and wild-type mice demonstrated almost indistinguishable infarct volumes and neurological deficiency scores." (PMID 23888142, 2013). "Furthermore, there is a negative correlation between SIRT1 levels and stroke scores, suggesting that SIRT1 may be predictive of stroke severity." (PMID 40724883, 2025). "In reverse, Sirt1 activity can also be determined by m6A methylation of its mRNA, however whether sexual dimorphism exists in alteration of m6A methylation after experimental stroke in the aged brain has never been assessed." (PMID 37191419, 2023). "Contrarily, stroke considerably elevated global PARP activity in the PTA muscle of WT mice, but not in the PTA muscle of SirT1+/+ mice, which inhibited PARP activity, as evidenced by reduced levels of global protein parylation." (PMID 32676579, 2020).
glioma (74 papers, 2011 to 2025). A benign or malignant brain and spinal cord tumor that arises from glial cells (astrocytes, oligodendrocytes, ependymal cells). "By depleting NAD+ to facilitate ATF3 activation and inhibiting SLC7A11 and GPX4, SIRT1 can enhance the susceptibility of glioma cells to ferroptosis." (PMID 39479446, 2024). "Up-regulation of miR-133b was associated with lower expression of Sirt1 and suppressed the invasion and proliferation of U87 glioma cells." (PMID 35071748, 2022). "It has also been reported that overexpression of SIRT1 is associated with a shorter overall survival of patients with glioma." (PMID 36361680, 2022). "Collectively, silencing circ-0082374 inhibited viability, migration, invasion, and glycolysis in glioma cells via a ceRNA mechanism involving miR-326 and SIRT1, thereby elucidating a novel pathogenic mechanism for glioma." (PMID 35883576, 2022). "We also find similar intermediary protein interactions through ESR1, AKT1 and SIRT1, whose activity are also associated with glioma." (PMID 28957313, 2017). "The results indicated that compound 5 decreased SIRT1 levels in C6 rat glioma cells at IC50/2 concentration, whereas compound 5 caused elevated SIRT1 levels compared to control at increased concentrations." (PMID 27879683, 2016). "Moreover, another research has indicated that miR-34a-modified MSCs can cause both glioma cell senescence and DNA damage via the control of Sirtuin 1 (SIRT1)." (PMID 40784879, 2025). "Higher levels of SIRT1 expression are associated with poorer overall survival in glioma patients." (PMID 40710366, 2025). "Moreover, SIRT1 has been implicated in promoting the viability of glioma tumour cell lines while concurrently inhibiting apoptosis." (PMID 38597418, 2024). "SIRT1 plays a significant role in glioma development, and its activity is regulated by SENP1 (sentrin-specific protease 1)." (PMID 40710366, 2025). "SIRT1 inhibitor exhibited an anticancer effect also on patient-derived glioma cells under 3D culture conditions." (PMID 39935420, 2025). "Specifically, SIRT1 inhibits the activity of NF-κB through deacetylation, which helps suppress pathways that lead to tumor growth and malignancy in gliomas." (PMID 40710366, 2025). "Inhibiting SIRT1 significantly reduces the proliferation of glioma cells and makes these cells more sensitive to temozolomide (TMZ)." (PMID 40710366, 2025). "Silencing SIRT1 increases epithelial markers and decreases mesenchymal markers, suggesting that SIRT1 promotes EMT (epithelial–mesenchymal transition) in glioma cells, facilitating their invasive capabilities." (PMID 40710366, 2025). "In glioma, miR-181a-5p upregulation promotes G1-phase arrest by targeting caspase-9, Bcl-2, and SIRT1, ultimately inhibiting cell proliferation." (PMID 40863219, 2025). "Targeting the SIRT1-hMOF pathway represents a novel therapeutic strategy to inhibit the tumor-supporting actions of microglia in glioma, potentially improving patient outcomes." (PMID 40710366, 2025). "Silencing SIRT1, achieved using siRNA, significantly inhibits the viability and invasion of the glioma cell lines U87 and U251, indicating its role in promoting glioma cell growth and spread." (PMID 40710366, 2025). "Downregulation of SIRT1 reverses the inhibitory effects of SENP1 depletion on the malignant phenotype of glioma cells, indicating that SIRT1 is crucial for maintaining the malignant characteristics of glioma cells." (PMID 40710366, 2025). "Glioma cells induce the nuclear localization of SIRT1 in microglia, which is essential for changes in histone acetylation." (PMID 40710366, 2025). "Conversely, activating SIRT1 with resveratrol increases cell proliferation, suggesting a differential response between glioma and normal cells." (PMID 40710366, 2025).
glioma (continued). "The interplay between SIRT1 and NF-κB is complex, as downregulation of NF-κB can reverse the activating effects of SIRT1 on glioma cell malignancy." (PMID 40710366, 2025). "SIRT1 inhibition leads to an increase in reactive oxygen species levels in glioma cells, which enhances the sensitivity of glioma cells to TMZ treatment." (PMID 40710366, 2025). "In glioma stem cells, SIRT1 acts as a pluripotent marker, exhibiting increased expression in stem media compared with normal media." (PMID 40710366, 2025). "SIRT1 has been shown to act as a crucial promoter in the maintenance and self-renewal properties of cancer stem cells (e.g., glioma, colorectal, breast, pancreatic CSCs, CML, and AML SCs)." (PMID 38397988, 2024). "In glioma cells, miR-138 decreases SIRT1 levels by targeting the 3' non-coding region, further inhibiting cell proliferation, migration, and invasion." (PMID 38044396, 2024). "In glioma cells, circ0082374 has a role in induction of cell viability, migration, invasion and glycolysis through regulation of miR-326/SIRT1 axis." (PMID 37441551, 2023). "In patient-derived IDH mutant glioma lines, overexpression of SIRT1 led to inhibition of cell growth." (PMID 36671446, 2022). "The results suggest high expression of SIRT1 as an independent prognostic factor which can predict OS in glioma patients (p < 0.05)." (PMID 36568393, 2022). "The downregulation of SIRT1 expression appears to be the mechanism by which hsa-circ-0076248 governs glioma development and invasion." (PMID 35883576, 2022). "SIRT1 has been detected overexpressed in GB cell lines, exhibiting an essential role in both glioma proliferation and chemoresistance." (PMID 36361680, 2022). "IF of 9L gliomas revealed heterogeneous upregulation of SIRT1, especially in hypoxic and peri-necrotic regions." (PMID 32118205, 2020). "Two days later, rats with 9L gliomas were treated either with SIRT1 specific inhibitor EX-527 (5 mg/kg, i.p.; N = 3) or with histone deacetylases class IIa specific inhibitor MC1568 (30 mg/kg, i.p.; N = 3) and 30 min later were injected i.v. with 2-[18F]BzAHA." (PMID 32118205, 2020). "Similar magnitudes of 2-[18F]BzAHA TACs were observed during the first few minutes after i.v. administration in normal brain structures expressing high levels of SIRT1 (i.e., nucleus accumbens and hippocampus) and the magnitudes of TACs observed in 9L gliomas." (PMID 32118205, 2020). "Histopathological features typical to gliomas display increased SIRT1 IF, particularly in hypoxic areas (ie, regions of microvessel proliferation, pseudopalisades, and peri-necrotic areas)." (PMID 32118205, 2020). "The role of SIRT1 expression–activity on progression and prognosis of gliomas can now be investigated more accurately using quantitative imaging of SIRT1 expression–activity in tumor tissue in vivo, in the native microenvironment of individual tumors." (PMID 32118205, 2020). "On the one hand, SIRT1 knockdown significantly inhibited glioma cell proliferation, migration, invasion, promoted its apoptosis and potentiated TMZ toxicity." (PMID 32373523, 2020). "In the current study, we demonstrate the efficacy of PET/CT/MRI with 2-[18F]BzAHA for imaging the expression–activity of SIRT1 and for noninvasive monitoring of EX-527 induced inhibition of SIRT1 activity in 9L intracerebral glioma models in rats." (PMID 32118205, 2020). "Sirtuin 1 (SIRT1) plays an important role in glioma progression, invasion, and treatment response and is a potential therapeutic target." (PMID 32118205, 2020).
glioma (continued). "In this study, SIRT1 was a target of miR‐181a; the expression levels and the biological function of SIRT1 in human glioma were regulated by miR‐181a." (PMID 30506951, 2019). "First, we analyzed the human glioma microarray GSE4290 dataset which demonstrated that the levels of SIRT1 were lower in the GBM group than in the low-grade glioma and non-tumor group." (PMID 31207928, 2019). "Real‐time RT‐PCR was performed to examine the mRNA level of Sirt1 in glioma and normal brain tissues." (PMID 30506951, 2019). "In the current study, we present evidence that the Sirt1 activator indicates growth restrictive and pro-apoptotic activity in glioma cells." (PMID 31319814, 2019). "On one hand, SIRT1 is characterized by some authors as a promoter factor in tumorigenesis of human glioma." (PMID 31119097, 2019). "In the current study, we investigated the role of circular RNA hsa_circ_0076248 in mediating the oncogenesis of glioma by sponging miR‐181a to modulate silent information regulator 1 (SIRT1) expression in vitro and in vivo." (PMID 30506951, 2019). "We explored the activity of the Sirt1 activator SRT2183 in glioma cell lines in terms of biological response." (PMID 31319814, 2019). "SIRT1 expression has been shown to be upregulated in a variety of CSCs both in vitro and in vivo, including glioma, breast, colorectal, and leukemia." (PMID 28994177, 2017). "This outcome pointed out that the effects of compound 5 on SIRT1 levels were dose dependent in C6 glioma cells." (PMID 27879683, 2016). "We also identified that HDAC1 and HDAC3expression levels were negatively correlated with survival time among gliomapatients, whereas the expression of HDAC4, HDAC5, HDAC6,HDAC11 and SIRT1 was positively correlated with survival time ofpatients with gliomas." (PMID 25791281, 2015). "Among all patients studied,the expression of HDAC1 and HDAC3 was inversely correlated withsurvival, whereas the expression of HDAC4, HDAC5, HDAC6,HDAC11 and SIRT1 was significantly and positively correlated withsurvival time of patients with gliomas." (PMID 25791281, 2015). "Recently, SIRT1 wassuggested to mediate cell proliferation in gliomas through the connection with theforkhead box M121." (PMID 25791281, 2015). "Knockdown of SirT1 expression enhanced radiosensitivity and radiation-induced apoptosis in glioma CD133-positive cells." (PMID 24223900, 2013). "We discovered that some targets of these microRNAs such as STAT3, PTBP1 or SIRT1 are differentially expressed in gliomas consistent with deregulation of microRNA expression." (PMID 21655185, 2011). "For example, lower amounts than expected regarding mRNA levels are noted for MDH1 in GBM and SIRT1 in gliomas; or the protein concentration was increased in glioma tissues, although the mRNA was only slightly modified (typically CCPG1, BCL2, MDM2 and PTBP1)." (PMID 21655185, 2011). "This suggests that PET/CT/MRI imaging with 2-[18F]BzAHA can be translated into clinical settings for selecting glioma patients who may benefit from SIRT1-targeted therapies and for monitoring the pharmacodynamics of SIRT1 inhibitors." (PMID 40710366, 2025). "Tumors derived from SIRT1-inhibited glioma cells show reduced growth compared with control tumors." (PMID 40710366, 2025). "In glioma cells, SIRT1’s impact on cell proliferation differs from that in normal astrocytes." (PMID 40710366, 2025). "The study also found that silencing SIRT1 increases epithelial markers and decreases mesenchymal markers (fibronectin and vimentin), suggesting that SIRT1 promotes EMT (epithelial–mesenchymal transition) in glioma cells, facilitating their invasive capabilities." (PMID 40710366, 2025). "This suggests that SIRT1’s inhibition of NF-κB is essential for controlling glioma cell behavior." (PMID 40710366, 2025). "SIRT1 is frequently overexpressed in glioma tissues, and its aberrant cytoplasmic localization correlates with enhanced proliferation, invasion, and therapy resistance in glioma cells." (PMID 40710366, 2025).